EMP3 (epithelial membrane protein 3 (MAM blood group))
Description:
Probably involved in cell proliferation and cell-cell interactions.
Synonyms: YMP
Tractability: Antibody: its Gene Ontology location is reachable by antibodies, with high confidence; UniProt predicts a signal peptide or a membrane-spanning region; the Human Protein Atlas places it where antibodies can reach.
Gene: Protein-coding gene on chromosome 19 (48,321,310 to 48,330,560, forward strand). Ensembl gene ENSG00000142227.
Subcellular location: Membrane
Subcellular location (Human Protein Atlas): Plasma membrane; Vesicles
Gene Ontology:
Molecular function: protein binding
Biological process: apoptotic process; bleb assembly
Cellular component: plasma membrane; membrane
Genetic constraint (gnomAD): Loss-of-function variants: 15 observed, 22.63 expected, observed/expected ratio (o/e) 0.66, 90% interval 0.44 to 1.02. The upper end of that interval is the gene's LOEUF score, 1.02, which puts it in group 4 of 6, group 1 being the genes least tolerant of losing a copy. Missense variants: 183 observed, 211.42 expected, observed/expected ratio (o/e) 0.87, 90% interval 0.77 to 0.98. Synonymous variants: 107 observed, 90.77 expected, observed/expected ratio (o/e) 1.18, 90% interval 1.01 to 1.38.
Homologues: Orthologues: chimpanzee EMP3 (99% identical), macaque EMP3 (99% identical), guinea pig EMP3 (98% identical), rabbit EMP3 (97% identical), pig EMP3 (95% identical), rat Emp3 (93% identical), mouse Emp3 (92% identical), dog EMP3 (66% identical), tropical clawed frog emp3 (60% identical), zebrafish emp3b (53% identical), zebrafish emp3a (52% identical). Paralogues in human: PMP22 (42% identical), EMP2 (39% identical), EMP1 (32% identical), LIM2 (20% identical), GSG1L (19% identical), GSG1L2 (18% identical), CLDND2 (15% identical), GSG1 (14% identical), NKG7 (14% identical), TMEM202 (14% identical).
Diseases named in the same sentence as EMP3 in open-access papers:
EMP3 is named in the same sentence as 49 diseases in open-access papers, as found by Europe PMC text mining. Sharing a sentence is not in itself a finding about the gene and the disease. The quoted sentences say what the papers report.
glioma (46 papers, 2010 to 2026). A benign or malignant brain and spinal cord tumor that arises from glial cells (astrocytes, oligodendrocytes, ependymal cells). "Differential expression of EMP3 in gliomas, Kaplan–Meier survival curves, diagnostic accuracy and prognostic prediction were analyzed by bioinformatics in the China Glioma Genome Atlas (CGGA) database and The Cancer Genome Atlas (TCGA) database." (PMID 38229014, 2024). "Our results elucidate that EMP3 is enriched in more malignant glioma subtypes and that univariate and multifactorial analyses show that EMP3 expression is an independent risk factor for OS in glioma patients." (PMID 38229014, 2024). "Histological grades, IDH mutation 40, 41, MGMT methylation 42-44 and EMP3 expression 31-33 were all validated prognostic factors of glioma." (PMID 34335936, 2021). "Loss of EMP3:CD44 interaction has also been reported in glioma, where ablation of EMP3 attenuates proliferation." (PMID 32678083, 2020). "Although EMP3 has been implicated as tumor suppressor gene in low grade glioma, its biological function in glioblastoma multiforme (GBM) still remains poorly understood." (PMID 27527869, 2017). "Although epithelial membrane protein 3 (EMP3) has been implicated as a candidate tumor suppressor gene for low grade glioma, its biological function in glioblastoma multiforme (GBM) still remains poorly understood." (PMID 27527869, 2017). "Because EMP3 could regulate immunological effects, we detected T cell composition and functional changes to clarify the immune mechanisms responsible for the prolonged survival time of glioma-bearing mice with EMP3 deficiency." (PMID 33964937, 2021). "Therefore, we aimed to explore the correlation between EMP3 levels and the status of immune infiltration to reveal the underlying mechanism in affecting the prognosis of gliomas." (PMID 34268874, 2021). "Moreover, the nomogram with EMP3 expression represented a practical approach to provide individualized risk assessment for glioma patients." (PMID 34268874, 2021). "Moreover, we believed that genes associated with histological grades, IDH mutation, MGMT methylation and EMP3 expression in glioma were also potential prognostic factors for glioma." (PMID 34335936, 2021). "In addition, EMP3 deficiency decreased PD-L1 expression, augmented anti-PD-1 treatment, and produced a survival advantage in glioma-bearing mice." (PMID 33964937, 2021). "In addition, it has been reported that EMP3 high expression is associated with a worse prognostic significance in OS in glioma patients." (PMID 32547876, 2020). "The higher frequency of EMP3 promoter hypermethylation in low- than high-grade gliomas, as well as its association with other well-known early genetic aberrations, indicates EMP3 methylation as an early epigenetic event during gliomagenesis, preceding the differentiation of precursors." (PMID 24083241, 2013). "However, transcriptional silencing of EMP3 in neuroblastoma and glioma cell lines is associated with aberrant methylation at exon 1 of EMP3; hypermethylation level is associated with poor 2-year survival and neuroblastoma-caused mortality, indicating a tumor-suppressing function." (PMID 35646656, 2022). "We analyzed the expression levels of EMP3 in different clinicopathological types of glioma based on mRNA-seq data from glioma patients in the CGGA and TCGA databases." (PMID 38229014, 2024). "In another study based on the bioinformatic analysis, low-grade glioma patients with low expression levels of EMP3 and CHI3L1 had a better prognosis." (PMID 39033204, 2024). "EMP3 was recently reported to be a tumor suppressor gene for several solid tumors, and is drawing attention as a novel prognostic marker, such as glioma, esophageal squamous cell carcinoma, colorectal cancer, and non-small cell lung cancer." (PMID 38229014, 2024). "The knockdown efficiency of EMP3 in glioma cells are detected by western blotting experiments (p < 0.01)." (PMID 38229014, 2024).
glioma (continued). "The most differentially expressed gene EMP3 (Epithelial membrane protein 3), which has been identified as an tumor suppressor in breast cancer, glioma and remains to be elucidated in colon cancer." (PMID 38729966, 2024). "Through comparative analysis of these groups, in the CGGA database, EMP3 was highly enriched in higher-grade gliomas (P < 0.0001) and IDH-wildtype gliomas (P < 0.0001)." (PMID 38229014, 2024). "EMP3 is enriched in high-grade gliomas and isocitrate dehydrogenase (IDH) wild-type gliomas.EMP3 can be used as a specific biomarker for diagnosing glioma patients." (PMID 38229014, 2024). "To investigate the prognostic, predictive value of EMP3 in glioma patients, we performed Kaplan- Meier and ROC curves and Cox proportional risk models based on the CGGA and TCGA databases." (PMID 38229014, 2024). "In non-glioma cells, EMP3 facilitates the activation of receptor tyrosine kinase (RTK) signaling pathway components, including the epidermal growth factor receptor (EGFR)." (PMID 37936247, 2023). "Further investigation has shown that EMP 3 transcriptional silencing occurs in neuroblastoma and glial tumors due to hypermethylation." (PMID 37629198, 2023). "Lastly, several independent studies have identified EMP3 as a prognostic gene for high-grade gliomas." (PMID 36837779, 2023). "EMP3 has low expression in the adult brain but among gliomas, it is exclusively highly expressed in IDH-wt GBM." (PMID 37936247, 2023). "The results of qRT-PCR showed that both CHI3L1 and EMP3 were expressed at low levels in tumor tissues, and the expression levels decreased with an increase in the glioma grade." (PMID 37887529, 2023). "The results showed that low-grade glioma patients with a low expression of EMP3 and CHI3L1 had a better prognosis, and EMP3 and CHI3L1 co-expression genes were correlated." (PMID 37887529, 2023). "To understand the co-expression genes of EMP3 and CHI3L1 regulation in glioma, we analyzed the conditions of EMP3 and CHI3L1-related genes." (PMID 37887529, 2023). "Patients with low-grade gliomas with low EMP3 and CHI3L1 expression levels had significantly better OS." (PMID 37887529, 2023). "To validate our analysis, we measured the expression of CHI3L1 and EMP3 in normal and low-grade glioma cells and glioblastomas." (PMID 37887529, 2023). "For instance, RBP1 and EMP3 participated in four and three gene pairs, respectively, and their dysregulation mechanisms in gliomas have been validated both experimentally and computationally." (PMID 36637205, 2023). "Although EMP3 was initially identified as a tumor suppressor in low-grade gliomas, its inhibitory effect remains controversial." (PMID 37887529, 2023). "Survival curves showed that in primary and recurrent gliomas, the survival time of patients with low levels of EMP3 was superior to that of patients with high levels of EMP3, with p < 0.001." (PMID 37887529, 2023). "We discover that EMP3 is an aberrant expression in the glioma cell line and determine how it contributes to the glioma migration and invasion." (PMID 37091145, 2023). "We found that the expression levels of EMP3 and CHI3L1 were higher in low-grade and high-grade gliomas than in normal brain tissue, and that the levels of EMP3 and CHI3L1 were much higher in high-grade gliomas than in normal brain tissue." (PMID 37887529, 2023). "To further understand the influence of mutations in the EMP3 and CHI3L1 genes on the prognosis of glioma patients, we performed a predictive analysis and a t-test, respectively." (PMID 37887529, 2023). "We pooled and analyzed the genetic information of 693 glioma patient samples from the CGGA database and found that the mutation rates of EMP3 and CHI3L1 were 1% and 1.2% in 693 patients." (PMID 37887529, 2023). "The results showed that low-grade glioma patients with low expression of EMP3 and CHI3L1 had better prognosis, and EMP3 and CHI3L1 co-expression genes were correlated." (PMID 37887529, 2023).
glioma (continued). "Results: low-grade glioma patients with a low expression of EMP3/CHI3L1 had a better prognosis, and the combination of EMP3/CHI3L1 is a new predictor for glioma patients." (PMID 37887529, 2023). "Consistent with previous studies that showed inhibition of RTK signaling in non-glioma cells upon EMP3 silencing, we observed higher EGF-induced EGFR degradation in our EMP3 KO cells." (PMID 37936247, 2023). "EMP3 bears hypermethylation mediated transcriptional silencing in both glioma and neuroblastoma 19q13 chromosome regions, it was initially considered a tumor suppressor gene in glioma and neuroblastoma." (PMID 36217151, 2022). "The expression of S100A4, EMP3, and PLAUR was increased in recurrent gliomas compared with primary gliomas as were the risk scores of recurrent gliomas." (PMID 35574375, 2022). "This study demonstrated that EMP3 is a novel independent predictor for clinical diagnosis, prognosis, and immune infiltration in glioma patients." (PMID 34268874, 2021). "This study demonstrated EMP3 as a novel predictor for clinical progression and clinical outcomes in glioma." (PMID 34268874, 2021). "To better understand the clinical role of EMP3 in patients with glioma, we analyzed tumor samples and clinical data from a total of 179 glioma patients." (PMID 34268874, 2021). "Another recent study reported that EMP3 directly interacts with TGFBR2 in glioma cells, which subsequently activates the TGF‐β/Smad2/3 pathway and enhances tumor progression in vitro and in vivo." (PMID 34268874, 2021). "To investigate the expression of EMP3 in gliomas at different stages, we analyzed EMP3 mRNA expression in 3 datasets." (PMID 34268874, 2021). "We found that glioma patients with CDHR1 low EMP3 high expression had worse clinical outcomes in TCGA and CGGA datasets." (PMID 34335936, 2021). "In the initial study, we focused on determining the mechanistic role and clinical value of EMP3 in glioma." (PMID 34268874, 2021). "Due to rare studies clarified the biological function and clinical value of EMP3 in glioma, here, we combined bioinformatic analysis and clinical data and established a nomogram predictive model with bicenter validation." (PMID 34268874, 2021). "Then, we analyzed EMP3 expression by IHC staining in samples from 179 glioma patients from 2013 to 2017." (PMID 34268874, 2021). "Next, it is interesting to identify the differentially expressed genes between IDH mutant and IDH wild type glioma patients or identify the genes most associated with MGMT methylation and EMP3 expression." (PMID 34335936, 2021). "Although EMP3 was initially identified as a tumor suppressor in low‐grade gliomas, its inhibitory role is still controversial." (PMID 34268874, 2021). "In our present study, we determined that EMP3 enhanced glioma progression and showed clinical value for prognostic prediction." (PMID 34268874, 2021). "The expression level of EMP3 is a stabilizing factor affecting the survival time of glioma patients." (PMID 34268874, 2021). "A previous study has shown that EMP3 is hypermethylated in approximately 20–40% of neuroblastoma and glioma cases, and plays a role in tumor suppression, which is also related with patients’ prognosis." (PMID 32857809, 2020). "Previous results suggested that the expression of EMP3 in glioma patients was controlled by DNA methylation." (PMID 32328202, 2020). "Consistent with previous studies, our study also supported an oncogenic role on the part of EMP3 in glioma." (PMID 32547876, 2020). "Here, we find two EMP3 and IGFBP2 associated genes TIMP1 and SERPINE1 are also suitable biomarkers for prognosis of glioma patients." (PMID 32328202, 2020). "The EMP3 gene has been proposed as a candidate tumor suppressor gene on 19q13.3 in several human solid tumors, such as gliomas, neuroblastoma, pheochromocytoma, non-small cell lung cancer, and esophageal squamous cell carcinoma." (PMID 27527869, 2017).
glioma (continued). "EMP3 has been proposed to be a tumor suppressor gene, which is silenced by hypermethylation on its promoter region in glioma, neuroblastoma, and non-small cell lung cancer." (PMID 26472188, 2015). "The EMP3 gene has been proposed to belong to the CpG island methylator phenotype, recently described in gliomas (G-CIMP)." (PMID 24083241, 2013). "Previous clinical observations in favor of EMP3 as a TSG in gliomas were based on EMP3 gene expression and knockdown studies, as well as on the demonstration of EMP3 hypermethylation as marker of poor outcome in neuroblastoma patients." (PMID 24083241, 2013). "Within tumors of the nervous system, DNA hypermethylation and aberrant expression of the EMP3 gene have been reported in both gliomas (24%) and neuroblastoma (39%)." (PMID 24083241, 2013). "The aim of this study was to investigate the EMP3 promoter hypermethylation status, as well as the EMP3 expression at protein level, in a large series of 229 human gliomas and in 16 GBM cell lines." (PMID 24083241, 2013). "Therefore, EMP3 is a reliable biological marker for predicting the prognosis of patients with glioma." (PMID 38229014, 2024). "It has been reported that EMP3 directly interacts with TGFBR2 in glioma cells." (PMID 37887529, 2023). "A previous study suggested that EMP 3 (a myelin-related gene located at 19q13.3) is a likely tumor-suppressor gene, because of its genomic deletion in the 19q13 chromosomal region in neural origin tumors, such as neuroblastoma and glial tumors." (PMID 37629198, 2023). "In summary, the knockdown of EMP3 expression inhibited the migration and invasion of glioma cells." (PMID 37091145, 2023). "Furthermore, a previous study has discovered that hypermethylation of EMP3’s promoter silences its production in glioma epigenetically and exhibits tumor suppressor features in glioblastoma." (PMID 37091145, 2023). "Methods: using Oncomine, Gene Expression Profiling Interactive Analysis (GEPIA), the Chinese Glioma Genome Atlas (CGGA), cBioPortal, LinkedOmics, and other databases, 693 glioma patients were screened to analyze the relationship between EMP3 and CHI3L1 expression and prognosis in glioma patients." (PMID 37887529, 2023). "In particular, EMP3 has been found to upregulate the surface expression of αvβ3 integrin, activate focal adhesion kinase and Src kinase, promote cell migration and invasion, promote tumor growth in vivo, and serve as a prognostic evaluation factor for glioma." (PMID 33875619, 2021). "Recent studies 16 showed that EMP3 expression, whose high-level expression is identified as a prognostic indicator of poor survival, is significantly higher in high-grade gliomas than in low-grade gliomas or normal brain tissues." (PMID 34093830, 2021). "EMP3 was significantly higher in higher‐grade glioma and predicted poor prognosis." (PMID 34268874, 2021). "While, glioma patients with CDHR1 high EMP3 low expression had better clinical outcomes." (PMID 34335936, 2021). "The expression level of EMP3 in glioma patients was significantly correlated with the OS rate." (PMID 34268874, 2021). "Then, we analyzed EMP3 expression in samples from 179 glioma patients from 2013 to 2017." (PMID 34268874, 2021). "For example, EMP3 was over-expressed in grade IV glioma (GBM)." (PMID 34335936, 2021). "In addition, high expressed EMP3 is of great predictive value and accuracy in prognostic prediction of glioma patients." (PMID 34268874, 2021). "However, several studies considered EMP3 to be a tumor suppressor gene in several solid cancers, including low‐grade glioma (LGG), esophageal carcinoma, and lung cancer." (PMID 34268874, 2021). "Among them, nine genes, including EMP3 were previously reported prognostic makers of glioma." (PMID 34335936, 2021).